MYH8 (myosin heavy chain 8)
Description:
Muscle contraction.
Synonyms: MyHC-peri; MyHC-pn; DA7; gtMHC-F
Tractability: PROTAC: ubiquitination databases record sites on it.
Gene: Protein-coding gene on chromosome 17 (10,390,322 to 10,421,950, reverse strand). Ensembl gene ENSG00000133020.
Subcellular location: Cytoplasm, myofibril
Subcellular location (Human Protein Atlas): Focal adhesion sites
Pathways (Reactome):
Muscle contraction: Striated Muscle Contraction
Gene Ontology:
Molecular function: ATP binding; ATP hydrolysis activity; microfilament motor activity; actin filament binding; myosin light chain binding; myosin phosphatase activity; structural constituent of muscle; cytoskeletal motor activity
Biological process: ATP metabolic process; muscle filament sliding; skeletal muscle contraction; muscle contraction
Cellular component: cytoplasm; cytosol; muscle myosin complex; myosin filament; myosin II complex; sarcomere; myofibril; myosin complex
Genetic constraint (gnomAD): Loss-of-function variants: 168 observed, 243.75 expected, observed/expected ratio (o/e) 0.69, 90% interval 0.61 to 0.78. The upper end of that interval is the gene's LOEUF score, 0.78, which puts it in group 3 of 6, group 1 being the genes least tolerant of losing a copy. Missense variants: 1,995 observed, 2,431 expected, observed/expected ratio (o/e) 0.82, 90% interval 0.79 to 0.85. Synonymous variants: 785 observed, 887.71 expected, observed/expected ratio (o/e) 0.88, 90% interval 0.83 to 0.94.
Homologues: Orthologues: chimpanzee MYH8 (99% identical), rabbit MYH8 (98% identical), rat Myh8 (97% identical), mouse Myh8 (97% identical), dog MYH8 (97% identical), guinea pig MYH8 (96% identical), pig MYH8 (95% identical). Paralogues in human: MYH2 (93% identical), MYH1 (92% identical), MYH4 (90% identical), MYH3 (85% identical), MYH13 (82% identical), MYH7 (81% identical), MYH6 (80% identical), MYH7B (67% identical), MYH15 (59% identical), MYH11 (42% identical), MYH9 (42% identical), MYH10 (41% identical), and 32 more.
Diseases named in the same sentence as MYH8 in open-access papers:
MYH8 is named in the same sentence as 31 diseases in open-access papers, as found by Europe PMC text mining. Sharing a sentence is not in itself a finding about the gene and the disease. The quoted sentences say what the papers report.
sarcopenia (4 papers, 2022 to 2025). Progressive decline in muscle mass due to aging which results in decreased functional capacity of muscles. "Among them, MYH8, HOXB2, C1QA, CDKN1A, and SLC38A1 are associated with sarcopenia, and in this study, LGR5, SERPINA5, and TPPP3 genes were found to be associated with Sarcopenia for the first time." (PMID 38229116, 2024). "Among them, the expression levels of SLPI and MYH8 in the sarcopenia group were significantly higher than those in the normal group (log2 FC > 1)." (PMID 36147639, 2022). "Notably, the expression levels of SLPI and MYH8 in the sarcopenia group were significantly higher than those in the normal group (log2 FC > 1)." (PMID 36050999, 2022). "In patients with sarcopenia, the expression of TPPP3, C1QA, LGR5, MYH8, and CDKN1A genes are upregulated, and the expression of SLC38A1, SERPINA5, and HOXB2 genes are downregulated." (PMID 38229116, 2024).
trismus-pseudocamptodactyly syndrome (4 papers, 2015 to 2022). "Mutations in the MYH8 gene are described in the Trismus-pseudocamptodactyly syndrome with autosomal dominant inheritance (OMIM: 158300)." (PMID 35079943, 2022). "In contrast to the large number of MYH3 mutations causing FSS and SHS, only a single MYH8 mutation (R674Q) has been identified in different families with trismus-pseudocamptodactyly syndrome." (PMID 26180627, 2015).
distal arthrogryposis (2 papers, 2018 to 2023). A muscle tissue disease characterized by congenital joint contractures of hand and feet. "Expression of several genes linked to motor neuronopathy and familiar amyotrophic lateral sclerosis (EPHA4, IGHMBP2, VAPB, BICD2, and DYNC1H1) or distal arthrogryposis (MYH8, ZC4H2, MUSK, RAPSN) were significantly upregulated or downregulated." (PMID 29727687, 2018).
arthrogryposis (1 paper, 2018). A rare, non-progressive congenital disorder characterized by multiple joint contractures which are present at birth. "Distal arthrogryposis is a cause of syndromic TEV that is characterized by variations in genes that encode for components of the muscle contractile complex (MYH3, TPM2, TNNT3, TNNI2, and MYH8), resulting in muscle contractures." (PMID 30134936, 2018).
Behcet disease (1 paper, 2016). A chronic, relapsing, multisystemic vasculitis characterized by mucocutaneous lesions, as well as articular, vascular, ocular and central nervous system manifestations. "Only three genes were found in common for both Dex and TAA: Myh8, Tpm3, identified as self-antigen in patients with Behcet's disease with posterior uveitis, and Elov1, with a role in fatty acid biosynthesis." (PMID 27429799, 2016).
centronuclear myopathy (1 paper, 2022). Centronuclear myopathy (CNM) is an inherited neuromuscular disorder characterized by clinical features of a congenital myopathy and centrally placed nuclei on muscle biopsy. "The authors did, however, find such a phenotype in biopsy specimens of centronuclear myopathy (CNM), a disease that also includes abundant small immature fibers; immunostaining revealed large numbers of MYH8+ fibers as well as HIF-1α target gene expression." (PMID 36453544, 2022).
chordoma (1 paper, 2025). Chordomas are rare malignant tumors arising from embryonic remnants of the notochord in axial skeleton. "The expression analysis identified significant downregulation of SPOCK3, NRK, MYH8, DLK1 and SLN, alongside upregulation of HLA-DQA1, GDA, CXCL11, CXCL9 and ADAMDEC1 in chordomas." (PMID 40386066, 2025).
Cirrhosis (1 paper, 2014). A chronic disorder of the liver in which liver tissue becomes scarred and is partially replaced by regenerative nodules and fibrotic tissue resulting in loss of liver function. "In addition, KIF5C, MYH8, SETD2 and UNC13C mutations were only found in HCC patients in the absence of cirrhosis (0% vs. 11%, p = 0.036 for all four genes)." (PMID 24988079, 2014).
endometriosis (1 paper, 2022). The growth of functional endometrial tissue in anatomic sites outside the uterine body. "They concluded that mutations of the MYH8 gene can play a role in the pathogenesis of endometriosis." (PMID 35079943, 2022).
lupus nephritis (1 paper, 2020). Glomerulonephritis in the context of systemic lupus erythematosus. "Lin and co found an association of selected MYH9 SNPs (although not rs3752462) with lupus nephritis occurrence, while in patients included in the already mentioned Corales study MYH8 SNPs did not correlate with lupus nephritis activity." (PMID 32873246, 2020).
metastatic tumors (1 paper, 2022). "Among these, FRAS1, PTPRC, MACF1 and MYH8 mutations have been found to be more enriched in other metastatic tumors." (PMID 36033490, 2022).
muscle atrophy (1 paper, 2014). The loss of muscle tissue due to inactivity or disease. "We focused this analysis on four genes that are closely linked to muscle atrophy (MSTN) and fast‐twitch, glycolytic muscle properties (ANKRD1, MYH8 and MYCBP2)." (PMID 24744911, 2014).
Myocardial fibrosis (1 paper, 2023). "These alternate approaches may also constitute avenues to explore the genotype-phenotype association of HCM, as one study applied radiomics analysis to T1 mapping to study the genotype-phenotype associations of sarcomeric (MYH8 and MYPBC3) HCM patients with respect to myocardial fibrosis." (PMID 38250029, 2023).
prognathia (1 paper, 2017). "Thus, MYH8 levels were found to be up- and down-regulated in retrognathia and prognathia patients, respectively." (PMID 28798667, 2017).
skin tumours (1 paper, 2019). "The rabbit skin tumours induced via blood infection displayed decreased expression of SLN, TAC1, MYH8, PGAM2, and APOBEC2 and increased expression of SDRC7, KRT16, S100A9, IL36G, and FABP9, as seen in tumours induced by local infections." (PMID 31340720, 2019).
tumor (5 papers, 2015 to 2025). "On the other hand, among the most oxidized proteins in healthy tissue compared to tumor were different isoforms of myosin, including MYH8 and MYH11." (PMID 40461450, 2025). "Consistent with RNA-seq data, the expression of SLN, TAC1, MYH8, and PGAM2 were down-regulated, whereas SDRC7, KRT16, S100A9, IL36G, and FABP9 were up-regulated in both blood (Animal #9, #11, and #12) and skin (Animal #6, #7, and #8)-induced tumours relative to normal skin controls." (PMID 31340720, 2019).
inflammatory myopathies (2 papers, 2020 to 2025). "Structural muscle genes (ACTA1, TTN) were reduced to levels similar to those in DM, while markers of muscle regeneration (NCAM1, PAX7, MYH3, MYH8) were only mildly increased compared to normal muscle, and lower than in other inflammatory myopathies." (PMID 41441888, 2025). "Other genes have additionally been reported to play important roles in skeletal muscle developments such as MYH2, MYH7 and MYH8 where myosin myopathies involving these genes have been widely reported." (PMID 32315303, 2020).
MYH8 also shares sentences with these, for which no sentence is quoted: cancer (2 papers); muscular dystrophy (2); cardiac disease (1); Carney complex (1); Carney complex variant (1); ciliopathy (1); Hepatic fibrosis (1); hypothyroidism (1); motor neuron disease (1); posterior uveitis (1); Retinitis pigmentosa 67 (1); Retrognathia (1); scoliosis (1); Strabismus (1).